ADM (adrenomedullin)
Diseases named in the same sentence as ADM in open-access papers (continued):
Sharing a sentence is not in itself a finding about the gene and the disease.
follicular thyroid cancers (1 paper, 2022). "We finally constructed glycolysis risk score (GRS) predictive models based on four targeting genes (ADM, CD44, MKI67 and TYMS), which were highly upregulated in tumor samples, including papillary and follicular thyroid cancers." (PMID 35528004, 2022).
gastric ulcer (1 paper, 2023). An ulcerated lesion in the mucosal surface of the stomach. "Adrenomedullin is widely expressed by the gastrointestinal epithelium and plays protective roles against gastrointestinal diseases, such as gastric ulcer or IBD, in animal models." (PMID 36799102, 2023).
gastritis (1 paper, 2020). Inflammation of the stomach. "Given the notable relationship between the level of ADM and the severity of gastric inflammation observed in H. pylori-infected patients, it is possible that ADM might serve as a novel diagnostic and prognostic biomarker for H. pylori-associated gastritis." (PMID 32184393, 2020). "Notably, higher ADM expression was strongly associated with more severe gastritis." (PMID 32184393, 2020). "In our study, we have, for the first time, demonstrated a pro-inflammation role of ADM in H. pylori infection and H. pylori-induced gastritis." (PMID 32184393, 2020). "In H. pylori-infected human gastric mucosa, ADM expression was positively correlated with the degree of gastritis; accordingly, blockade of ADM resulted in decreased inflammation within the gastric mucosa of H. pylori-infected mice." (PMID 32184393, 2020). "Adrenomedullin (ADM) is a multifunctional peptide that is expressed by many surface epithelial cells, but its relevance to Helicobacter pylori (H. pylori)-induced gastritis is unknown." (PMID 32184393, 2020).
glaucoma (1 paper, 2012). Increased pressure in the eyeball due to obstruction of the outflow of aqueous humor. "For example, there is increased ADM in the vitreous humor of patients with diabetes, in patients with primary open-angle glaucoma, and in the aqueous humor of patients with uveitis and vitreoretinal disorders, and patients with retinitis pigmentosa have increased plasma ADM." (PMID 22690112, 2012).
glomerulonephritis (1 paper, 2021). A renal disorder characterized by damage in the glomeruli. "In the first step, the authors found plasma ADM levels were higher and urinary levels were lower in patients with glomerulonephritis comparing to the healthy control group." (PMID 33540505, 2021). "Plasma ADM concentration was also assessed in patients with glomerulonephritis." (PMID 33540505, 2021).
gout (1 paper, 2021). A condition characterized by painful swelling of the joints, which is caused by deposition of urate crystals. "Through clinical verification, we found that pro-ADM can be used as an inflammation-related biomarker for acute attacks of gout, providing new ideas for the diagnosis and treatment of gout." (PMID 35116032, 2021). "We found that pro-ADM can be used as a new inflammation-related biomarker to predict and diagnose the acute attacks of gout in male patients, which provides new insights for the development of it." (PMID 35116032, 2021). "We found that the expression of pro-ADM in the gout group and hyperuricemia group was higher than that in the healthy group, and the difference was statistically significant." (PMID 35116032, 2021). "Finally, through the detection of pro-ADM levels in clinical samples, we confirmed that pro-ADM is involved in gout flare." (PMID 35116032, 2021). "We speculate that the involvement of ADM in gout may be related to the following aspects." (PMID 35116032, 2021). "This may also be one of the ways ADM participates in the regulation of gout." (PMID 35116032, 2021). "In addition to gout, pro-ADM may also be affected by other factors." (PMID 35116032, 2021). "As an emerging indicator of inflammation, pro-ADM has not been studied to show changes in patients with gout." (PMID 35116032, 2021).
hepatocellular carcinoma (1 paper, 2025). A malignant tumor that arises from hepatocytes. "These collective findings establish that ADM downregulation suppresses hepatocellular carcinoma cell proliferation." (PMID 41450464, 2025). "To investigate ADM’s influence on hepatocellular carcinoma cell proliferation, migration, and invasion, we established an Huh7 cell line with ADM knockdown." (PMID 41450464, 2025). "Colony formation experiments revealed the sh-ADM + sorafenib group formed substantially fewer colonies than the sh-NC + sorafenib group, confirming ADM knockdown markedly enhances sorafenib’s capacity to inhibit hepatocellular carcinoma cell proliferation." (PMID 41450464, 2025). "Wound healing and Transwell migration assays revealed that in Huh7 cells, the sh-ADM group demonstrated significantly reduced migration rates compared to the sh-NC group, indicating ADM expression reduction impairs hepatocellular carcinoma cell migratory capacity." (PMID 41450464, 2025). "Furthermore, Transwell invasion assays performed in Huh7 cells showed fewer cells in the sh-ADM group traversed the chamber relative to the sh-NC group, establishing that ADM downregulation attenuates hepatocellular carcinoma cell invasive capacity." (PMID 41450464, 2025).
hydrops fetalis (1 paper, 2022). Hydrops fetalis is a severe and challenging fetal condition usually defined as the excessive accumulation of fetal fluid within the fetal extravascular compartments and body cavities that manifests as edema, pleural and pericardial effusion and ascites. "Mice lacking functional adrenomedullin show lethal hydrops fetalis and cardiovascular abnormalities, indicating that adrenomedullin substantially contributes to development of endothelial barrier function." (PMID 35741064, 2022).
hyperlipidemia (1 paper, 2022). "PA was used to mimic fatty acid stimulation and to verify the roles of ADM in cardiomyocyte damage induced by hyperlipidemia." (PMID 35745637, 2022).
hyperuricemia (1 paper, 2021). An abnormally high level of uric acid. "The expression of serum pro-ADM of the acute gout group and the hyperuricemia group was higher than that of the control group, and the difference was statistically significant." (PMID 35116032, 2021).
IgA nephropathy (1 paper, 2021). "In addition, the lack of glomerular ADM may be associated with the proliferation of glomerular mesangial cells, which is observed in patients with IgA nephropathy." (PMID 33540505, 2021).
inflammatory bowel disease (1 paper, 2024). A spectrum of small and large bowel inflammatory diseases of unknown etiology. "Additionally, ADM antibodies have exhibited beneficial effects in rodent models of inflammatory bowel disease (IBD) and have been tested in clinical trials involving human patients." (PMID 39200990, 2024).
liver fibrosis (1 paper, 2017). "We previously reported that RAMP2 is the key modulator of the endogenous vasoprotective peptide adrenomedullin, and that vascular endothelial cell-specific RAMP2 knockout mice show vascular inflammation and liver fibrosis." (PMID 29022011, 2017).
lupus nephritis (1 paper, 2021). Glomerulonephritis in the context of systemic lupus erythematosus. "The plasma ADM concentration was elevated in lupus nephritis and correlated with systemic lupus erythematosus disease activity." (PMID 33540505, 2021).
malignant hypertension (1 paper, 2023). Severe hypertension that is characterized by rapid onset of extremely high blood pressure and hypertension-mediated organ damage. "The heightened ADM levels in malignant hypertension could be linked to the condition severity and can be mitigated with suitable antihypertensive therapy." (PMID 38069140, 2023). "The significant increase in plasma ADM concentration in subjects with malignant hypertension was identified." (PMID 38069140, 2023).
metastatic tumors (1 paper, 2025). "In metastatic tumors, pathway and TF analyses revealed strong hypoxia-inducible factor-1α–driven hypoxia activation, influencing glycolysis (SLC2A1, SLC2A3, PGK1, PDK1, PGM1, and ALDOA), angiogenesis (ANGPTL4 and ADM), and survival in low oxygen (BNIP3, BNIP3L, and NDRG1)." (PMID 40736012, 2025).
Myocardial fibrosis (1 paper, 2025). "MSCs can also alleviate myocardial fibrosis by secreting antifibrotic factors (such as adrenomedullin [ADM]), with ADM-overexpressing MSCs showing reduced MMP2 levels and improved cardiac function." (PMID 40323498, 2025).
Neonatal sepsis (1 paper, 2018). Systemic inflammatory response to infection in newborn babies. "In an earlier study, at the cut-off value of 3.9 pmol/ml, the sensitivity of Pro-ADM in detecting neonatal sepsis was 91.6%, its specificity was 87.4%, its positive predictive value was 91.3%, and its negative predictive value was 90.4%." (PMID 30154872, 2018).
neuroendocrine carcinoma (1 paper, 2022). A malignant neuroendocrine neoplasm composed of cells containing secretory granules that stain positive for NSE and chromogranin. "However, in line with our results, plasma ADM has been correlated with tumor progression in neuroendocrine carcinomas of various origin." (PMID 35267617, 2022).
oral cancer (1 paper, 2014).
oral squamous cell carcinoma (1 paper, 2023). "In the SCC-25 cell line, which is derived from oral squamous cell carcinoma, the ADM expression level was significantly elevated." (PMID 37675228, 2023).
oropharyngeal squamous cell carcinoma (1 paper, 2024). "In oropharyngeal squamous cell carcinoma, ADM expression has been associated with bad prognosis." (PMID 39200990, 2024).
ovarian tumors (1 paper, 2013). "Adrenomedullin also upregulates α5β1 integrin in ovarian tumors and patients with high adrenomedullin expression showed a higher incidence of metastasis and poor outcomes, indirectly further suggesting a role of α5β1 integrin in the aggressiveness of ovarian tumors." (PMID 24216697, 2013).
peritonitis (1 paper, 2019). Inflammation of the peritoneum (tissue that lines the abdominal wall and covers most of the organs in the abdomen). "Twenty-four hours of peritonitis and septic shock induced changes in the ADM pathway, with greater expression of ADM in the heart and lung and of CRLR and RAMP 2 in the heart and kidney." (PMID 31093784, 2019).
pituitary adenomas (1 paper, 2003). "Furthermore, patients with Cushing's disease resulting from pituitary adenomas were found to have significantly higher circulating ADM levels than healthy controls." (PMID 14612905, 2003).
prostate tumours (1 paper, 2017). "Studies have linked adrenomedullin (AM), calcitonin (CT) and calcitonin gene-related peptide (CGRP) to the spread of prostate tumours to the bone." (PMID 28845385, 2017).
psoriatic arthritis (1 paper, 2010). Joint inflammation associated with psoriasis. "We cannot assume a complete specificity of the adrenomedullin effect in RA because we have not tested other FLSs derived from psoriatic arthritis, as an example." (PMID 20942979, 2010).
Renal amyloidosis (1 paper, 2022). A form of amyloidosis that affects the kidney. "Although these results indicated higher ADM levels in patients with a homozygous M694V mutation, further studies are needed to relate ADM levels and renal amyloidosis." (PMID 36010070, 2022).
renovascular hypertension (1 paper, 2023). High blood pressure secondary to renal artery stenosis. "Significantly higher concentration of ADM was observed in malignant and renovascular hypertension, suggesting a potential contribution of the renin–angiotensin system (RAS) activation in the elevation of ADM levels." (PMID 38069140, 2023).
retinal ischemia (1 paper, 2010). A ischemic disease that involves the retina. "Adrenomedullin may also play a role in the neovascularization process that occurs after retinal ischemia." (PMID 20181139, 2010).
retinitis pigmentosa (1 paper, 2012). Retinitis pigmentosa (RP) is an inherited retinal dystrophy leading to progressive loss of the photoreceptors and retinal pigment epithelium and resulting in blindness usually after several decades. "Conversely, ADM’s ability to cross the BRB may account for the increased plasma levels of ADM seen in patients with retinitis pigmentosa." (PMID 22690112, 2012).
sarcoma (1 paper, 2020). A usually aggressive malignant neoplasm of the soft tissue or bone. "ADM, a vasodilating peptide known as a regulator in the pathophysiology of cardiovascular disease, was recently found to have the ability to promote the growth of subcutaneously transplanted sarcoma 180 tumor cells, and ADM inhibitors were shown to be useful for the management of sarcoma growth." (PMID 32873319, 2020).
Sicca syndrome (1 paper, 2022). "Sicca syndrome is poorly characterised and often considered to be heterogeneous in aetiology, but we identified surprisingly strong associations of symptoms with BMI and some proteins, especially ADM." (PMID 35589331, 2022).
Syncope (1 paper, 2018). A transient loss of consciousness (i.e., characterized by a rapid onset, a short duration, and a spontaneous and complete recovery) due to cerebral hypoperfusion. "Finishing the protocol without developing syncope was related to stable adrenomedullin plasma levels after centrifugation with axis of rotation placed above the head in comparison with increased adrenomedullin levels in non-finishers at the same position." (PMID 30774604, 2018).
systemic sclerosis (1 paper, 2023). A chronic disorder, possibly autoimmune, marked by excessive production of collagen which results in hardening and thickening of body tissues. "NAC has been shown to decrease the frequency and severity of Raynaud’s phenomenon (RP) attacks and digital ulcers (DU) in patients with systemic sclerosis (SSc), with a significant reduction in plasma adrenomedullin concentrations." (PMID 38136193, 2023).
thromboembolic disease (1 paper, 2025). "D-dimer levels are used to rule out thromboembolic disease, while copeptin and adrenomedullin (MR-proADM) may be used as measures of the patient`s stress level." (PMID 38960969, 2025).
ulcerative colitis (1 paper, 2024). An inflammatory bowel disease involving the mucosal surface of the large intestine and rectum. "In ulcerative colitis, increased expression of adrenomedullin in epithelial cells and fibroblasts leads to mast cell activation via MRGPRX236." (PMID 38168103, 2024).
tumor (146 papers, 2002 to 2026). "Across these datasets, ADM was predominantly expressed in malignant epithelial tumor cells and tumor-associated macrophages, rather than in stromal or lymphoid compartments." (PMID 40547013, 2025). "This is when symptoms begin to appear in many patients due to the neoplastic disorder caused by tumor cells secreting molecules, such as adrenomedullin (AM), which inhibits insulin secretion by β-cells." (PMID 40487412, 2025). "Building on this foundation, we further elucidate the pathways and signaling cascades associated with ADM’s involvement in the initiation, progression, and metastasis of various tumor tissues." (PMID 40565016, 2025). "ADM was identified as a key gene in the high-risk group, correlating with tumor stage, immune suppression, and resistance to immunotherapy." (PMID 40547013, 2025). "Further clinical characteristics analysis revealed that ADM expression was significantly associated with tumor stage and pathological grade using BEST website, indicating its potential involvement in LUAD progression." (PMID 40547013, 2025). "A growing body of research indicates that targeting ADM and its associated signaling pathways represents a promising strategy for inhibiting tumor development by preventing angiogenesis, proliferation, and migration." (PMID 40565016, 2025). "Abundant staining of pSMAD3 and ACVR2B in tumor‐associated ADM extended our question to the role of activin A in tumor‐associated ADM." (PMID 37083240, 2023). "Increasing systemic levels of vasoactive peptides, including pro-ADM, are associated with improved tumor response in metastatic colorectal carcinoma patients treated with a bevacizumab-containing regimen." (PMID 35135489, 2022). "Analyses in cell models and xenograft tumours both demonstrated that AR upregulated Yes associate protein 1 (YAP)-adrenomedullin (AM) signalling." (PMID 31852972, 2019). "Blocking ADM secretion from cancer cells or tumor-associated macrophages (TAMs) using a specific antibody or ADM antagonist (AMA) inhibits tumor angiogenesis and growth." (PMID 27391260, 2016). "Overexpression of ADM was significantly associated with poorer OS (P<0.001) and tumor recurrence (P<0.01)." (PMID 26043778, 2015). "Adrenomedullin is a highly conserved peptide implicated in a variety of physiological processes ranging from pregnancy and embryonic development to tumor progression." (PMID 22582036, 2011). "Consequently, beyond the therapeutic strategy of directly targeting ADM and its receptor system, the inhibition of associated signaling pathways can also yield anti-tumor effects." (PMID 40565016, 2025). "Among them, ADM exhibited positive association with metabolic reprogramming, particularly pyrimidine and purine metabolism and negative association with fatty acid metabolism, suggesting its potential role in tumor metabolic regulation." (PMID 40547013, 2025). "Moreover, there is increasing evidence that adrenomedullin and its receptors are associated with the development and spread of tumours, resulting in the proposal of blockades for adrenomedullin and its receptors as potential treatments in multiple cancers." (PMID 36835377, 2023). "The fact that loss of adrenomedullin expression in tumor cells affected tumor cell growth only in co-culture with endothelial cells suggested that endothelial cells mediate regulation of tumor cell proliferation by tumor cell–derived adrenomedullin." (PMID 36374225, 2023). "Also, we found less accumulation of α‐SMA‐positive fibroblasts near tumor‐associated ADM regions from the Inhba‐si group." (PMID 37083240, 2023). "However, it is unclear if tumor‐associated ADM becomes cancerous but will constitute PDAC tumor in part by secreting activin A and promoting the accumulation of fibroblasts as demonstrated by our study and human invasive PDAC." (PMID 37083240, 2023).